5_8S_rRNA (5.8S ribosomal RNA )
Synonyms: RNA5-8SP
Gene: Ribosomal RNA gene on chromosome 14 (16,057,472 to 16,057,622, forward strand). Ensembl gene ENSG00000283274.
Gene Ontology:
Molecular function: structural constituent of ribosome
Cellular component: ribosome
Homologues: Orthologues: chimpanzee 5_8S_rRNA (96% identical), zebrafish 5_8S_rRNA (89% identical), zebrafish si:dkeyp-3b12.15 (89% identical), zebrafish 5_8S_rRNA (88% identical), rat 5_8S_rRNA (87% identical), rat 5_8S_rRNA (86% identical), rat 5_8S_rRNA (85% identical), rat 5_8S_rRNA (84% identical), rat 5_8S_rRNA (83% identical), rat 5_8S_rRNA (82% identical), mouse Gm54867 (81% identical), rat 5_8S_rRNA (81% identical), and 1 more. Paralogues in human: 5_8S_rRNA (99% identical), 5_8S_rRNA (95% identical), 5_8S_rRNA (91% identical), RNA5-8SN1 (91% identical), RNA5-8SN2 (91% identical), RNA5-8SN3 (91% identical), RNA5-8SN4 (91% identical), RNA5-8SN5 (91% identical), 5_8S_rRNA (87% identical), 5_8S_rRNA (85% identical).